ACVR2B (activin A receptor type 2B)
Description:
Transmembrane serine/threonine kinase activin type-2 receptor forming an activin receptor complex with activin type-1 serine/threonine kinase receptors (ACVR1, ACVR1B or ACVR1c). Transduces the activin signal from the cell surface to the cytoplasm and is thus regulating many physiological and pathological processes including neuronal differentiation and neuronal survival, hair follicle development and cycling, FSH production by the pituitary gland, wound healing, extracellular matrix production, immunosuppression and carcinogenesis. Activin is also thought to have a paracrine or autocrine role in follicular development in the ovary. Within the receptor complex, the type-2 receptors act as a primary activin receptors (binds activin-A/INHBA, activin-B/INHBB as well as inhibin-A/INHA-INHBA). The type-1 receptors like ACVR1B act as downstream transducers of activin signals. Activin binds to type-2 receptor at the plasma membrane and activates its serine-threonine kinase. The activated receptor type-2 then phosphorylates and activates the type-1 receptor. Once activated, the type-1 receptor binds and phosphorylates the SMAD proteins SMAD2 and SMAD3, on serine residues of the C-terminal tail. Soon after their association with the activin receptor and subsequent phosphorylation, SMAD2 and SMAD3 are released into the cytoplasm where they interact with the common partner SMAD4. This SMAD complex translocates into the nucleus where it mediates activin-induced transcription. Inhibitory SMAD7, which is recruited to ACVR1B through FKBP1A, can prevent the association of SMAD2 and SMAD3 with the activin receptor complex, thereby blocking the activin signal. Activin signal transduction is also antagonized by the binding to the receptor of inhibin-B via the IGSF1 inhibin coreceptor.
Synonyms: ACTR-IIB; ACTRIIB; HTX4
Tractability: Small molecule: a structure with a bound ligand is known; a high-quality ligand is known; it has a binding pocket of medium quality; it belongs to a druggable protein family. Antibody: a drug acting on it is in phase 2 or 3 trials; UniProt places it where antibodies can reach, with high confidence; its Gene Ontology location is reachable by antibodies, with high confidence; UniProt predicts a signal peptide or a membrane-spanning region. PROTAC: ubiquitination databases record sites on it; a small molecule that binds it is known. Other modalities: an approved drug acts on it.
Target class: Kinase; TKL protein kinase STKR family; Protein Kinase; Enzyme; TKL protein kinase group; TKL protein kinase STKR Type 2 subfamily
Gene: Protein-coding gene on chromosome 3 (38,453,890 to 38,493,142, forward strand). Ensembl gene ENSG00000114739.
Subcellular location: Cell membrane
Pathways (Reactome):
Developmental Biology: Regulation of signaling by NODAL; Signaling by NODAL
Signal Transduction: Signaling by Activin; Signaling by BMP
Gene Ontology:
Molecular function: activin receptor activity, type II; growth factor binding; protein binding; protein serine/threonine kinase activity; activin binding; activin receptor activity; ATP binding; kinase activator activity; protein kinase activity; protein serine/threonine/tyrosine kinase activity; transmembrane receptor protein serine/threonine kinase activity
Biological process: activin receptor signaling pathway; anterior/posterior pattern specification; BMP signaling pathway; intracellular iron ion homeostasis; negative regulation of transcription by RNA polymerase II; positive regulation of activin receptor signaling pathway; positive regulation of bone mineralization; positive regulation of osteoblast differentiation; regulation of DNA-templated transcription; signal transduction; artery development; blood vessel remodeling; cell surface receptor protein serine/threonine kinase signaling pathway; cellular response to growth factor stimulus; lymphangiogenesis; lymphatic endothelial cell differentiation; negative regulation of adipose tissue development; negative regulation of cold-induced thermogenesis; negative regulation of ossification; pattern specification process; retina vasculature development in camera-type eye; trophoblast cell migration; venous blood vessel development; developmental process
Cellular component: cytoplasm; plasma membrane; protein-containing complex; receptor complex; activin receptor complex; membrane
Genetic constraint (gnomAD): Loss-of-function variants: 18 observed, 65.36 expected, observed/expected ratio (o/e) 0.28, 90% interval 0.19 to 0.41. The upper end of that interval is the gene's LOEUF score, 0.41, which puts it in group 1 of 6, group 1 being the genes least tolerant of losing a copy. Missense variants: 482 observed, 703.94 expected, observed/expected ratio (o/e) 0.68, 90% interval 0.63 to 0.74. Synonymous variants: 298 observed, 290.04 expected, observed/expected ratio (o/e) 1.03, 90% interval 0.93 to 1.13.
Homologues: Orthologues: chimpanzee ACVR2B (100% identical), dog ACVR2B (99% identical), mouse Acvr2b (99% identical), rat Acvr2b (99% identical), macaque ACVR2B (98% identical), guinea pig ACVR2B (98% identical), pig ACVR2B (98% identical), tropical clawed frog acvr2b (84% identical), zebrafish acvr2ba (74% identical), zebrafish acvr2bb (73% identical). Paralogues in human: ACVR2A (68% identical), BMPR2 (34% identical), TGFBR2 (34% identical), ACVR1C (30% identical), ACVR1B (29% identical), TGFBR1 (28% identical), BMPR1B (28% identical), AMHR2 (28% identical), ACVRL1 (28% identical), BMPR1A (27% identical), ACVR1 (27% identical).
Diseases named in the same sentence as ACVR2B in open-access papers:
ACVR2B is named in the same sentence as 94 diseases in open-access papers, as found by Europe PMC text mining. Sharing a sentence is not in itself a finding about the gene and the disease. The quoted sentences say what the papers report.
Cachexia (21 papers, 2013 to 2026). Severe weight loss, wasting of muscle, loss of appetite, and general debility related to a chronic disease. "Notably, pharmacologically improving muscle mass by administration of ACVR2B/Fc was also shown to rescue C26-associated cachexia and significantly prolong survival." (PMID 27259276, 2016). "As DLK1 functions as a selective inhibitor of ACVR2B, it may have the potential to be adapted as a more targeted therapy for counteracting the loss of muscle associated with anti-obesity drugs, muscle wasting disorders, or cachexia." (PMID 40593645, 2025). "The authors observed that sex-specific differences in endogenous levels of Activin A contribute to sex dimorphisms in PDAC-induced cachexia, as well as the differential outcomes of ACVR2B-Fc treatment in attenuating tumor-induced Activin." (PMID 36314781, 2022). "Future studies should further explore the mechanisms by which counteracting ACVR2B signalling can preserve fat mass in models of experimental cachexia." (PMID 33200567, 2020). "The ability of ACVR2B/Fc to counteract cancer-induced cachexia has been demonstrated in a number of studies." (PMID 31438622, 2019). "Our goal in this study is to use a metabolomics approach to understand the biochemical mechanisms by which ACVR2B/Fc mitigates chemotherapy-induced cachexia." (PMID 31438622, 2019). "Since that initial discovery, ACVR2B/Fc has been evaluated in a number of pre-clinical studies of both cancer and chemotherapy-induced cachexia with significant preservation of skeletal muscle." (PMID 31438622, 2019). "Identification of these pathways provides important insights into the mechanism by which ACVR2B/Fc protects against chemotherapy-induced cachexia." (PMID 31438622, 2019). "Similarly, Huot and colleagues reported that ACVR2B inactivation prevented multi-organ perturbations secondary to cachexia in metastatic colon cancer." (PMID 36676129, 2023). "Interestingly, a number of studies have shown that preservation of skeletal muscle mass by targeting of the ACVR2B signalling is efficacious at prolonging survival in experimental cancer cachexia." (PMID 33200567, 2020). "In the present study, we sought to determine whether targeting ACVR2B signalling by administration of ACVR2B/Fc was able to combat cachexia in a newly generated mouse model of CRC‐induced LM." (PMID 33200567, 2020). "In particular, Acvr2b, FoxO1, and STAT3 all had spearman correlations of at least 0.63 with three of these weights indicating that both the transcriptions factors and TGFβ signaling may play a role in pancreatic cancer associated cachexia." (PMID 30513792, 2018). "In order to better understand the consequence of ACVR2B/Fc administration to healthy animals and mice treated with Folfiri, we also assessed the circulating levels of IL-6 and activin A, previously reported to play a major role in promoting cachexia and in the regulation of muscle and bone mass." (PMID 29089584, 2017). "Importantly, we also show that administration of ACVR2B/Fc or MEK1 inhibitors prevents Folfiri-associated muscle atrophy in in vitro conditions, thus supporting the idea that promoting muscle anabolism or preventing MAPKs activation may potentially counteract chemotherapy-derived cachexia." (PMID 27259276, 2016). "Moreover, the present study only examined the benefits of ACVR2B/Fc on male mice bearing HCT116 LM, and as sexual dimorphism has been observed in the progression of cachexia in CRC, future studies should investigate whether ACVR2B/Fc benefits equally span across both sexes." (PMID 33200567, 2020).
Obesity (10 papers, 2014 to 2025). Accumulation of substantial excess body fat. "Several studies have examined the effects of ACVR2B/Fc treatment on insulin signaling in obesity and diabetes, but this is the first report demonstrating the effects on cachexia." (PMID 31438622, 2019). "As for patients with COPD, the Activin A Receptor Type 2B (ACVR2B) and Transforming Growth Factor Beta 1 (TGFβ1), which were the key modulators of BMPR2 pathway, were significantly downregulated, as well as the obesity-related gene Apelin Receptor Early Endogenous Ligand (APELA)." (PMID 37886639, 2023).
Nephroblastoma (4 papers, 2015 to 2025). An embryonal neoplasm characterized by the presence of epithelial, mesenchymal, and blastema components. "In nephroblastoma, it inhibits tumor growth by downregulating ACVR2B, and it further limits angiogenesis in renal tumors through targeting ECR1." (PMID 40087755, 2025). "In nephroblastomas, ACVR2B was found to be a direct target of miR-215-5p." (PMID 33255928, 2020). "The downregulating miR-192 may contribute to nephroblastoma development by targeting ACVR2B." (PMID 40087755, 2025).
pancreatic cancer (4 papers, 2014 to 2023). "Since then, the same potential of ACVR2B antagonists, including ACVR2B-Fc and other inhibitors, such as microRNA-194, has also been discovered in different cancers, including pancreatic cancer and clear cell kidney carcinoma." (PMID 36769292, 2023). "According to these findings, our network revealed that ACVR2B, GFRA1, and MTHFR are the most gene transcripts that are regulated by miRNAs and their relationships to pancreatic cancer were confirmed previously." (PMID 24895587, 2014). "The miR-24 has been reported as most important miRNA and genes such as ACVR2B, GFRA1, and MTHFR are most involved in pancreatic cancer." (PMID 24895587, 2014).
renal childhood neoplasms (4 papers, 2016 to 2017). "For example, the common target ACVR2B of five miRNAs (miRNA-192, miRNA-194, miRNA-215, miRNA-200c and miRNA-141) is strongly expressed in renal childhood neoplasms." (PMID 28177900, 2017). "What's more, their common target ACVR2B was found to have strong expression in renal childhood neoplasms." (PMID 27533456, 2016). "ACVR2B is strongly expressed in renal childhood neoplasms and could be readily targeted." (PMID 28871274, 2017).
breast carcinoma (3 papers, 2011 to 2023). "BMPR1B and ACVR2B were positively correlated with ER in Luminal A subtype (ER+, HER2-) breast cancer." (PMID 37333824, 2023). "In four main subtypes of breast cancer, elevated expression of BMPR1B and ACVR2B were seen in Luminal A subtype, while BMP4, GDF15 and ACVR1B were higher in Luminal B, TGFBR1 and BMP8A were higher in HER2 positive, BMP2, BMP6 and GDF5 were higher in TNBC." (PMID 37333824, 2023). "On the other hand, both ACVR2B and DAND5 were negatively correlated with EMT in overall breast cancer." (PMID 37333824, 2023). "We have previously reported that all six BMP specific receptors (ACVR1, BMPR1A, BMPR1B, ACVR2A, ACVR2B, and BMPR2) are uniformly expressed among the breast cancer cell lines studied here." (PMID 22118688, 2011). "Furthermore, higher levels of BMP2, BMP6 and GDF5 were revealed in triple negative breast cancer (TNBC) whilst BMP4, GDF15, ACVR1B, ACVR2B and BMPR1B were relatively higher in Luminal type BC." (PMID 37333824, 2023).
clear cell kidney carcinoma (3 papers, 2019 to 2023). "Another study indicated that lower expression of miR‐194‐5p and higher expression of MALAT1, ACVR2B were related with advanced TNM stage, larger tumour size (≥4 cm) and poor prognosis of patients with clear cell kidney carcinoma." (PMID 33484504, 2021). "ACVR2B has also been reported to be a member of the MALAT1/miR-194-5p/ACVR2B signaling axis, which promotes clear cell kidney carcinoma (KIRC) progression." (PMID 31886217, 2019).
colorectal cancer (3 papers, 2014 to 2023). A primary or metastatic malignant neoplasm that affects the colon or rectum. "One study in colorectal cancer reported that ACVR2B once bound to BMP3 thereafter resistant cell apoptosis via Smad-dependent signalling." (PMID 37333824, 2023).
lymphoma (3 papers, 2012 to 2017). A malignant (clonal) proliferation of B- lymphocytes or T- lymphocytes which involves the lymph nodes, bone marrow and/or extranodal sites. "This identified upregulation of TGFβ signalling as the most affected molecular pathway in Eμ-Myc;shBcor lymphomas (Bonferroni corrected P=0.0058), with enhanced expression of TGFβ pathway members (Cited1, Bambi, Acvr2b, Smad3, Mapk12, Tgfb2)." (PMID 28262675, 2017).
muscular dystrophy (3 papers, 2014 to 2023). Muscular dystrophy (MD) refers to a group of more than 30 genetic diseases characterized by progressive weakness and degeneration of the skeletal muscles that control movement. "ACVR2B/Fc, an inhibitor of the Activin Receptor 2B signaling, has been shown to preserve muscle mass and prolong survival in tumor hosts, and to increase bone mass in models of osteogenesis imperfecta and muscular dystrophy." (PMID 29089584, 2017).
anemia (2 papers, 2015 to 2025). A reduction in the number of red blood cells, the amount of hemoglobin, and/or the volume of packed red blood cells. "Thus, when decoy receptors for ACVR2A or ACVR2B were used in clinical trials, activin A signaling was inhibited with improved anemia and bone disease." (PMID 26047946, 2015). "Notably, patient samples of the lower-risk MDS subtypes refractory anemia and refractory anemia with ring sideroblasts, in which anemia is the predominant clinical presentation, have significantly elevated levels of GDF11 and ACVR2B transcripts." (PMID 40424086, 2025).
chronic kidney disease (2 papers, 2022 to 2024). Impairment of the renal function secondary to chronic kidney damage persisting for three or more months. "Western blotting showed that treatment with Bacteroides plebeius reduced the expression of MSTN, SMAD2 and ACVR2B, and these expression levels were increased in rats with chronic renal failure‐associated protein depletion." (PMID 36458537, 2022).
endometrial cancer (2 papers, 2015 to 2016). Primary or metastatic malignant neoplasm involving the endometrium (mucous membrane that lines the endometrial cavity). "Presently, phase I studies with an ACVR2B Fc fusion protein (STM 434) in combination with liposomal doxorubicin are underway in patients with advanced tumors, including endometrial cancer (NCT02262455)." (PMID 27223076, 2016). "Interestingly, an ACVR2B Fc fusion protein (STM 434) has entered phase 1 studies in combination with liposomal doxorubicin in patients with ovarian cancer or other advanced tumors, including endometrial cancer (NCT02262455)." (PMID 26384307, 2015).
glioma (2 papers, 2019 to 2023). A benign or malignant brain and spinal cord tumor that arises from glial cells (astrocytes, oligodendrocytes, ependymal cells). "In order to figure out the oncogene associated with glioma, we selected five genes to preform qRT-PCR experiments, including XPR1, QKI, CREB5, ACVR2B and ABL2." (PMID 37407973, 2023). "In addition, previous studies revealed that XPR1, ACVR2B and CREB5 could promote progression of diverse cancers, but they were not reported in glioma." (PMID 37407973, 2023).
hepatocellular carcinoma (2 papers, 2022 to 2024). A malignant tumor that arises from hepatocytes. "The results showed that miR-139-5p and TGFBR3 were significantly down-regulated in hepatocellular carcinoma tissues, and miR-582-3p, ACVR2B, SMAD2 and SMAD5 were up-regulated in hepatocellular carcinoma tissues." (PMID 35386287, 2022). "We selected 2 differentially expressed miRNAs (miR-139-5p and miR-582-3p) and four hub mRNAs (ACVR2B, SMAD2, SMAD5, and TGFBR3) for qRT-PCR verification in 20 hepatocellular carcinoma tissues and 20 adjacent tissues." (PMID 35386287, 2022).
kidney neoplasm (2 papers, 2017 to 2018). A benign or malignant neoplasm affecting the kidney. "For example, miR‐21 was found up‐regulated in kidney neoplasms 68, whereas five miRNAs including miR‐192, miR‐215, miR‐194, miR‐141 and miR200c, which have a common target gene (ACVR2B), had a lower expression in kidney neoplasms." (PMID 29272076, 2018). "For example Activin A receptor type 2B (ACVR2B), an important component of the TGF-β pathway, is often highly expressed in renal neoplasms; several miRNAs have been noted as downregulated and have been confirmed to directly target this gene." (PMID 28103887, 2017).
lung carcinoma (2 papers, 2021 to 2022). "Most BMPs/BMP receptors were downregulated in lung cancer tissues, except BMP7, ACVR1C, and ACVR2B which were upregulated in one dataset." (PMID 34036102, 2021).
muscle atrophy (2 papers, 2016 to 2019). The loss of muscle tissue due to inactivity or disease. "Moreover, the present observations provide a strong rationale for testing ACVR2B/Fc or MEK1 inhibitors in combination with anticancer drugs as novel strategies aimed at preventing chemotherapy-associated muscle atrophy." (PMID 27259276, 2016).
myocardial infarction (2 papers, 2020 to 2021). Gross necrosis of the myocardium, as a result of interruption of the blood supply to the area, as in coronary thrombosis. "When utilizing Mstn-deficient mice, or a decoy for its receptor ACVR2B-Fc, the absence of Mstn signal improves cardiac function after myocardial infarction." (PMID 34576046, 2021).
prostate carcinoma (2 papers, 2022 to 2026). A carcinoma that arises from epithelial cells of the prostate gland. "Other highly connected proteins included ACVR2B (13 edges) and CRKL (12 edges), which were linked to most of the miRNA hubs, but currently have limited evidence supporting a specific role in prostate cancer." (PMID 41598250, 2026). "Within the prostate-associated protein subset, CDK6 was the most connected node (14 edges), followed by ACVR2B, KMT2A, and PIK3R1, each with 13 edges (which ranks potential biomarkers and their impacts in prostate cancer)." (PMID 41598250, 2026). "Of the 32 target hub genes, 4 were mapped to cell signalling pathways including ACVR1 and ACVR2B in TGF-beta signalling, CDKN1A and GSK3B in ErbB signalling (adj.P val = 0.016) and CDKN1A and GSK3B genes in Prostate cancer pathways (adj." (PMID 36468011, 2022).
Splenomegaly (2 papers, 2019 to 2020). Abnormal increased size of the spleen. "GDF11 is known to negatively affect erythrocyte maturation, and its blockade by ACVR2B-Fc increases extramedullary hematopoiesis leading to splenomegaly." (PMID 30765322, 2019).